IL21R (interleukin 21 receptor)
Diseases named in the same sentence as IL21R in open-access papers (continued):
Sharing a sentence is not in itself a finding about the gene and the disease.
infection (37 papers, 2013 to 2026). The state of being infected such as from the introduction of a foreign agent such as serum, vaccine, antigenic substance or organism. "Significant associations between SNVs on IL21R and infection with A. lumbricoides and levels of anti-Ascaris lumbricoides IgE and IgG4 and parasite antigen induced production of IL-5 and IL-10 by PBLs." (PMID 33692795, 2021). "We explored if genetic variants in WSB1/IL21R might influence Th2-associated immune responses during A. lumbricoides infection using immunological markers of susceptibility and resistance to infection including production of Th2 cytokines in vitro." (PMID 33692795, 2021). "Similarly, IL-21R KO mice exhibited slightly increased weight loss, possibly due to elevated cytokines late after infection." (PMID 25849970, 2015). "In this paper, we have used mouse models of erythrocytic P. chabaudi and P. yoelii 17X(NL) infections in combination with IL-21/IL-21R deficiency to show that IL-21 from CD4+ T cells is required to eliminate Plasmodium infection by activating protective, long-lasting B-cell responses." (PMID 25763578, 2015). "The functions of IL-21R on epithelial cells are unknown, but stimulation of these cells with IL-21 could contribute to decreased susceptibility to infection." (PMID 24358128, 2013). "SNVs in WSB1 (rs7213148 and rs8065359) and IL21R [rs115350516 (A allele) and rs3093308 (T allele)] were associated with increased production of A. lumbricoides-specific IgE and could be potentially linked to greater resistance to infection." (PMID 33692795, 2021). "IL-21R−/− mice showed lower infiltration of pulmonary total Mφ, alveolar macrophages, and interstitial macrophages compared with WT mice following infection." (PMID 37628738, 2023). "The results revealed that pulmonary Mφ (CD45+F4/80+ cells) exhibit a basal expression of IL-21R, which steadily increases to day 7 and 14 post-infection (p.i.)." (PMID 37628738, 2023). "One of the most crucial attributes of Mφ responses lies in their ability to secrete cytokines, so we further analyzed how IL-21/IL-21R influence the Mφ polarization after infection." (PMID 37628738, 2023). "Our meta-analyses indicated that five out of the eight significantly identified genes (CD40, ICOS-L, SLAMF1, CD84, IL-21R) were downregulated continuously during infection." (PMID 37146079, 2023). "To further address the early stages of the IL-21 response during infection, we examined expression of the IL-21 receptor (IL-21R) in primary human tonsil B lymphocytes at baseline (day 0) in each tonsil specimen." (PMID 36569889, 2022). "In the present study, IL21R was significantly upregulated at all three time points, corroborating its protective role in immunity and infection." (PMID 36439120, 2022). "Recent researches revealed that IL-21/IL-21R plays both proinflammatory and anti-inflammatory roles in infection and inflammation." (PMID 35693111, 2022). "IL-21/IL-21R was documented to participate in the regulation of multiple infection and inflammation." (PMID 35693111, 2022). "We found an increased expression of IL7R, IL23R (both strains) and IL21R (Eystrup only) by cDC1 and cDC2 subsets, while pDC downregulated IL7R (Eystrup) and upregulated IL21R following infection (both CSFV strains)." (PMID 32733474, 2020). "In contrast, it appears that the IL-21/IL-21R signaling axis also played critical roles in the development of TH2 immune response following infection with the intestinal luminal nematodes, Nippostrongylus brasiliensis and H. polygyrus." (PMID 31867283, 2019). "(C) IFNα levels in BAL fluid were measured by ELISA 4 hr after infection in mice pretreated with control Fc or IL-21R-Fc." (PMID 30969166, 2019). "(B) Histology of lungs in control Fc or IL-21R-Fc pre-treated mice at 4 and 24 hr post-infection (bar in upper left panel = 500 μm; bar in inset = 10 μm)." (PMID 30969166, 2019).
infection (continued). "In contrast, blockade of the IL-21R during the hypo-responsive phase of L. sigmodontis infection increased resistance to infection and enhanced parasite-specific B cell and antibody responses." (PMID 31815932, 2019). "Crypt hyperplasia and loss of goblet cells accompanied by significant submucosal edema with significantly higher perivascular inflammatory cells were more noticeable in the distal colon of WT mice 9 days after infection than in the Il21r-/- mice." (PMID 30818341, 2019). "Our findings indicated that Il21r-/- mice had significantly higher (2 logs) bacterial burden in the feces as compared with WT controls, both early and late in the infection, although the peak bacterial load was comparable." (PMID 30818341, 2019). "While the WT controls were able to control the infection with C. rodentium by day 21 p.i., Il21r-/- mice had an impaired ability to clear the enteric infection with this pathogen." (PMID 30818341, 2019). "Our analysis showed four distinct clusters between uninfected and infected WT and Il21r-/- mice 9 days after infection with C. rodentium." (PMID 30818341, 2019). "Considering that both type I- and type II-specific ISGs were impaired in infected Il21r-/- mice, we investigated which type of interferon was required for the control of infection." (PMID 30818341, 2019). "Four week following aerosol infection, IL-21R−/− T cells are reduced in the blood and lungs relative to WT T cells, and produce less IFNγ and TNF, similar to experiments performed with IL-12R−/− CD8+ T cells." (PMID 27819295, 2016). "As a result of this failed protection, all mice receiving IL-21R KO CD8+ T cells succumbed to infection while 100% of mice receiving WT CD8+ T cells with Th17 cells survived long-term." (PMID 27695083, 2016). "We observed that IL-21R−/− cells lag behind WT cells starting 13 days post-infection, indicating that IL-21 signaling promotes efficient CD8+ T cell priming." (PMID 27819295, 2016). "In agreement with the flow cytometric data, the lungs of IL-21R−/− mice contained fewer perivascular and peribronchiolar lymphoid aggregates during early infection when compared to WT mice." (PMID 27819295, 2016). "M. tuberculosis infection induced qualitatively similar lung lesions in WT and IL-21R−/− mice dominated by macrophages and lymphocytes, and accompanied by small areas of neutrophilic infiltrates and occasional necrotic cells as infection progressed over time." (PMID 27819295, 2016). "P. chabaudi-infected Il21-/- and Il21r-/- mice showed significantly greater spleen cellularity compared with WT C57BL/6 controls as early as 32 days post-infection, and dramatic splenomegaly at later time points." (PMID 25763578, 2015). "Similar to the overall kinetics of MHV68 infection, the kinetics of the germinal center response were similar in wt and IL-21R-/- mice, peaking at day 18 post-infection." (PMID 25875847, 2015). "Using IL-21R deficient mice, we show that IL-21 signaling is required for efficient establishment of MHV68 infection." (PMID 25875847, 2015). "In wt mice, nearly 90% of the infected B cells exhibited a germinal center phenotype at the peak of infection (day 18), whereas less than 70% of infected B cells in IL21R-/- mice had a germinal center phenotype at the peak of infection." (PMID 25875847, 2015). "At day 20 post-infection, the frequency of reactivating cells from wt mice had contracted to 1 in 9,162 cells reactivating virus, whereas in IL21R-/- mice the frequency had fallen further to 1 in 5.1x105 cells." (PMID 25875847, 2015). "This defect in establishment of MHV68 infection is intrinsic to B cells, as MHV68 preferentially establishes infection in IL-21R sufficient B cells in mixed bone marrow chimeric mice." (PMID 25875847, 2015). "At days 16 and 18 post-infection, whereas the frequency increased to ca. 1 in 7,500 cells in wt mice, it dropped dramatically in IL-21R-/- mice to ca. 1 in 2.3x105 cells." (PMID 25875847, 2015).
infection (continued). "To delineate the role of IL-21 signaling in MHV68 infection, we characterized infection in IL-21R-/- mice." (PMID 25875847, 2015). "To this end, we measured IAV-specific IgG and IgM in sera collected from infected IL-21R KO and WT mice at day 10 post-infection." (PMID 25849970, 2015). "Since γδ T cells have also been previously documented to be capable of producing IL-17 during IAV infection, we analyzed IL-17-producing γδ T cells in the infected lungs of IL-21R KO mice at various times post infection." (PMID 25849970, 2015). "At day 32 post-infection, the numbers of B cells in the spleen of Il21-/- and Il21r-/- mice were reduced compared to WT C57BL/6 controls, and this was reflected in the numbers of mature (M), transitional 1 (T1) and transitional 2 (T2) B cells." (PMID 25763578, 2015). "At day 14 post-infection, the frequency of splenocytes capable of reactivating virus was slightly lower in IL21R-/- mice, with 1 in 60,885 reactivating cells compared to 1 in 21,515 in wt mice." (PMID 25875847, 2015). "Although the overall kinetics of infection were similar in wild type (wt) and IL-21R-/- mice, the magnitude was greatly reduced in IL-21R-/- mice." (PMID 25875847, 2015). "Similar to results observed with Il21r−/− mice, intraperitoneal infection of Il21−/− mice with cysts from the ME49 strain of T. gondii did not result in increased susceptibility to acute or chronic disease over the time course examined." (PMID 23667536, 2013). "Prior studies have established that Il21r−/− mice infected with T. gondii survive for at least 100 days post-infection, yet these mice display a defect in serum IgG." (PMID 23667536, 2013). "The increased expression of IL-21R in the vagina after HSV-2 infection supports that IL-21 is induced at the innate stages of infection." (PMID 24358128, 2013). "We next assessed the impact of increased Treg cell numbers in IL-21R−/− mice and treated both IL-21R−/− and WT mice with DT between days 8 to 15 post infection with 2000 PFU LCMV-DOC." (PMID 23696736, 2013). "IL-21R KO mice exhibited increased vaginal viral titers on day 2 and 3 post infection (p.i.)and subsequently developed significantly higher disease scores and a lower survival rate compared to WT mice." (PMID 24358128, 2013). "Age > 60, a clinical factor associated with the TLT subtype, was associated with 57 upregulated genes, including BCR signaling genes, IL6 (related to infection), and IL21R (different from TLT vs. ME), and 141 downregulated genes including EPCAM, AR, WT1, and CD28." (PMID 39866884, 2025). "Based on broad effects on target cells, IL-21/IL-21R was demonstrated to have pleiotropic effects on humoral and cellular immunity as well as additional inflammatory pathways, implying its regulatory properties in infection, autoimmunity, and cancer." (PMID 35693111, 2022). "In addition, documented to recruitment neutrophil during inflammation, S100A8 mRNA expression was reduced in lungs of IL-21R−/− mice after infection, which also partly accounted for lower neutrophil chemotaxis when IL-21/IL-21R blocked." (PMID 35693111, 2022). "Resistant IL-21R−/− mice showed impaired neutrophil recruitment to the site of infection." (PMID 35693111, 2022). "In contrast to potential roles played by the IL-21/IL-21R signaling axis in protective immunity during infection with trematodes, earlier studies demonstrated that the IL-21/IL-21R signaling pathway promotes the induction of tissue damage following Schistosoma spp." (PMID 31867283, 2019). "Moreover, histological analysis of lung sections showed that mice treated with IL-21R-Fc had enhanced inflammation and significantly increased pathology and neutrophil scores by 4 hr after infection, analogous to what we observed above in the Il21r KO mice." (PMID 30969166, 2019).
infection (continued). "In WT mice, infection with Pneumonia Virus of Mice (PVM), in which host defense substantially depends on adaptive immunity, results in a marked inflammatory response by 5 or 6 days, and we previously showed that this is substantially diminished after infection of Il21r KO mice." (PMID 30969166, 2019). "We used MBMC mice to determine whether IL-21 signaling is required for T cell expansion during infection, a strategy that facilitates the direct comparison of WT and IL-21R−/− T cells in the same inflammatory environment in vivo." (PMID 27819295, 2016). "Correspondingly, cDCs from Il21r−/− mice had lower expression of pro-IL-1β after PVM infection." (PMID 26269257, 2015). "To this end, we evaluated antigen specific CD8+ T cell responses in IL-21R KO mice at various days post infection by employing fluorescently labeled tetramers that recognize TCRs specific for the IAV immunodominant epitopes, NP366 or PA244, presented by MHC class I molecules." (PMID 25849970, 2015). "Another factor that may be contributing to reduced infection in IL-21R-/- mice is altered viral gene expression." (PMID 25875847, 2015). "In line with the absence of IgG antibodies, there was also a loss of both P. chabaudi-specific IgG antibody-secreting-cells (ASC) in the BM, and of P. chabaudi-specific IgG MBC in the spleen at day 32 post-infection in both Il21-/- and Il21r-/- mice when compared with WT C57BL/6 controls." (PMID 25763578, 2015). "However, the numbers of B220+CD138high plasmablasts in BM from Il21-/- and Il21r-/- mice, and the numbers of B220–CD138high plasma cells in BM from Il21-/- mice were reduced at day 32 post-infection compared to those of WT C57BL/6 controls." (PMID 25763578, 2015). "We found that cytokines typically of effector T cell origin (e.g. IFNγ, IL-10, and TNF) were not significantly altered in WT and KO mice, although there was a general trend toward higher cytokine levels in IL-21R KO mice late after infection (i.e. day 14 p.i.)." (PMID 25849970, 2015). "Analysis of the MHV68 infected (YFP+) plasma cell population showed that, although there were significantly fewer total infected splenocytes in IL-21R-/- mice, approximately 20% of infected splenocytes in both wt and IL-21R-/- mice had a plasma cell phenotype at day 14 post-infection." (PMID 25875847, 2015). "This disparity between overall infection and the germinal center response in IL-21R-/- mice was reflected in a significant reduction in the percentage germinal center B cells that were infected in IL-21R-/- mice." (PMID 25875847, 2015). "However, there is a significant reduction in the percentage of YFP+ B cells that have a germinal center phenotype in IL-21R-/- mice, arguing against the direct infection model." (PMID 25875847, 2015). "The slightly higher numbers of Tfh cells in Il21-/- and Il21r-/- at day 120 post-infection compared with those in WT C57BL/6 mice might have been a consequence of the on-going infection promoting continued T cell activation." (PMID 25763578, 2015). "However, upon infection the population of IL-21R−/− Treg cells expanded 3-fold over that of WT Treg cells to represent 30% versus 10% of all CD4+ T cells, respectively." (PMID 23696736, 2013). "One possible explanation for the different outcomes using Il21r−/− and Il21−/− mice may be the route of infection used, as oral infection may have had an affect on dissemination of the parasite as well as priming of the acute response." (PMID 23667536, 2013). "We discovered different mRNA expression level of NF-κB p65 subunit in two groups of mice after infection, suggesting this signaling pathway could represent as potential target for IL-21/IL-21R regulation on neutrophil response during C. muridarum infection, while its role is to be tested further." (PMID 35693111, 2022). "Importantly, MHV68 infection was significantly higher in Ly5.1+ IL-21R+/+ B cells." (PMID 25875847, 2015).
infection (continued). "In contrast, IL-21R deficiency did not affect the kinetics of a P. chabaudi AS single infection." (PMID 25996913, 2015). "It has previously been shown that the level of infection in B cells is proportional to the magnitude of the germinal center response, so it is somewhat surprising that the defect in infection was much greater than the defect in generating germinal center B cells in IL-21R-/- mice." (PMID 25875847, 2015). "At day 32 post-infection, the numbers of Ter119+ erythrocytic cells in the spleen in the absence of IL-21 signaling were dramatically increased, thus contributing to the large splenomegaly observed in Il21-/- and Il21r-/- mice from day 32 post-infection onwards." (PMID 25763578, 2015). "Importantly, this infection-triggered expansion of the Treg cell population was greatly inhibited by IL-21R signaling in Treg cells, thus defining a novel role for IL-21 in preventing T cell exhaustion and viral persistence via limiting virus-driven Treg cell proliferation." (PMID 23696736, 2013). "The IL-21R was expressed by the vaginal epithelia and the increase in IL-21R expression was due to increased receptor expression in the vaginal epithelial cells, suggesting a role for IL-21 signalling through the IL-21R at this early and innate stage of infection." (PMID 24358128, 2013). "More specifically, IFITM1—interferon-induced transmembrane protein 1, IL21R—interleukin 21 receptor and IFITM3—the interferon-induced transmembrane protein 3 (IFITM3), were overexpressed, as observed after infection with precHP viruses." (PMID 34835129, 2021). "CD4 T cells in the brain produce IL-21 during early infection by the gliatropic JHMV coronavirus and CD8 T cells upregulate the IL-21 receptor (IL21R); notably, IL21R−/− CD8 T cells have impaired granzyme B and IFNγ production." (PMID 32971931, 2020). "(A) WT mice were treated intratracheally with 50 μg of control Fc (from IgG1) or IL-21R-Fc protein for 2 days prior to infection with MRSA and lung CFU were quantitated at 4 and 24 hr post-infection with MRSA." (PMID 30969166, 2019). "Analogous to the Il21r KO mice, WT mice receiving IL-21R-Fc had greater clearance of MRSA at both 4 and 24 hr after infection than was observed in mice treated with the control Fc." (PMID 30969166, 2019). "Both the alpha chain (IL-21R) and the common gamma chain (γc) of the IL-21 receptor were constitutively expressed by pulmonary CD4+ and CD8+ T cells, before and after infection." (PMID 27819295, 2016). "Following adoptive transfer of WT or IL-21R−/− TB10Rg CD8+ T cells, we tracked T cell priming in the lung-draining LN following infection." (PMID 27819295, 2016). "At day 14 post-infection, the percentage of YFP+ splenocytes was higher in wt mice than in IL-21R-/- mice (0.053% and 0.013% respectively), but the difference was not statistically significant." (PMID 25875847, 2015). "To address this issue, we generated mixed bone marrow (BM) chimeras by reconstituting lethally irradiated WT (CD45.1+) mice with a 1∶1 ratio of WT (CD45.1+) and IL-21R−/− (CD45.2+) BM, and evaluated their Treg cell responses to infection with LCMV-DOC." (PMID 23696736, 2013). "Moreover, the immune-suppressive signals, such as suppression of IL21R on STAT3, PI3K mediated inhibition of inflammation by dopamine upon infection, as well as the inhibition of NLRC3 on STING during a steady state." (PMID 34290708, 2021). "To address the role played by the IL-21/IL-21R signaling axis in CD4+ T cells in host protection after C. rodentium infection, we assessed the bacterial burden, the infection kinetics and survival rates in conditional knockout mice with a CD4+ T cells-specific deletion of STAT3 activity." (PMID 30818341, 2019).